MYOC (myocilin)
Diseases named in the same sentence as MYOC in open-access papers (continued):
Sharing a sentence is not in itself a finding about the gene and the disease.
glaucoma (continued). "List of some pathogenic/likely pathogenic glaucoma-associated myocilin missense mutations." (PMID 38152303, 2023). "In the case of myocilin-associated glaucoma, rare familial variants are highly penetrant." (PMID 36579626, 2023). "Glaucoma-linked myocilin mutations in fact, may impinge on the exosomal pathway, affecting the ability of TM cells to process cell debris from the AH and resulting in an increased outflow resistance and elevated IOP." (PMID 37113676, 2023). "The authors hypothesize that myocilin is an astrocyte membrane-associated cytoskeletal-linking protein that supports astrocyte cell shape and that dysregulation of myocilin in glaucoma may lead to structural alterations of the optic nerve head." (PMID 37760829, 2023). "Glaucoma is a heterogeneous disease, and genetic risk for glaucoma is complex and extends well beyond myocilin, but patients with the highest combination of known genetic risk variants are diagnosed on average 5 years earlier than those with fewer genetic risk variants." (PMID 36579626, 2023). "Initially, familial genetics studies identified a rare OLF mutation with a dominant inheritance pattern alongside detailed clinical data and, soon thereafter, a case–control study of glaucoma patients and age-matched controls identified probable glaucoma-causing myocilin variants." (PMID 36579626, 2023). "In addition, several transgenic mice were created based on already discovered mutations in glaucoma patients, e.g., mutations in the genes MYOC/GLC1A, OPTN/GLC1E, and the tryptophan-aspartic acid repeat domain 36 (GLC1G)." (PMID 37791268, 2023). "Study demonstrated that Ca dysregulation results in the wild-type myocilin misfolding initially and may further contribute broadly to glaucoma-associated endoplasmic reticulum stress." (PMID 37851631, 2023). "Previous support for the V329M variant as benign comes primarily from the observation that methionine is the corresponding residue in Danio rerio myocilin, but the mutation has also been documented among glaucoma patients, including one diagnosed with juvenile OAG." (PMID 36579626, 2023). "Indeed, most of the myocilin-associated glaucoma mutations are missense clustered in the OLF domain." (PMID 38152303, 2023). "Estimates suggest that myocilin-associated glaucoma accounts for 3-4% of OAG cases." (PMID 36579626, 2023). "The biological function of the glaucoma-associated protein myocilin remains poorly known." (PMID 36077382, 2022). "Variable disease severity in MYOC mutation carriers has recently been shown to be affected by polygenic effects, and glaucoma variation caused by some TEK mutations may be due to the modifying effects of an SVEP1 variant." (PMID 36453543, 2022). "Myocilin, a key gene in glaucoma, when mutated can overwhelm the ERAD and build up in the TM." (PMID 35624748, 2022). "In glaucoma, variation in MYOC can cause early-onset glaucoma." (PMID 36672852, 2022). "Nevertheless, mutation of MYOC only leads to glaucoma lesions in eyes." (PMID 36267417, 2022). "Myocilin is mainly existed in TM cells and only causes glaucoma when mutated." (PMID 36267417, 2022). "OPTN, TANK binding kinase 1 (TBK1), and Myocilin (MYOC) are genes linked to glaucoma." (PMID 36589756, 2022). "Mutations in the MYOC gene are an important cause of glaucoma with dominant inheritance (Liuska." (PMID 36012492, 2022). "MYOC gene mutations leads to glaucoma mainly through TM cell death inducing IOP elevation." (PMID 35615698, 2022). "In addition, the study of a transgenic Drosophila line also supported a role for aggregation of myocilin in the endoplasmic reticulum and activation of the unfolded protein response in myocilin-associated glaucoma." (PMID 36077382, 2022). "Myocilin (MYOC) mutations have been linked to primary open-angle glaucoma (POAG)." (PMID 36429042, 2022).
glaucoma (continued). "Therefore, the correlations between the stabilities of these mutated myocilin proteins and age at glaucoma diagnosis of patients who carry the mutations should be similar as well." (PMID 34828408, 2021). "The two opposite effects induced by ER stress, combined with the natural variation of myocilin production in the general population, may explain why there is a weak correlation between protein stability of mutated myocilin and age of glaucoma diagnosis." (PMID 34828408, 2021). "Finally, other than the 20 MYOC mutations we examined in this study, there are many more known MYOC mutations that have been implicated in glaucoma." (PMID 34828408, 2021). "However, we still lack a clear understanding of its biological function and how mutant myocilin underlies glaucoma pathogenesis." (PMID 33573230, 2021). "ER stress may be induced by numerous factors, and the one strictly associated with glaucoma pathogenesis may constitute the mutation in myocilin (MYOC) gene, as one of the major genetic factors responsible for POAG development and progression." (PMID 33925820, 2021). "A correlation between age at diagnosis of glaucoma and MYOC mutations can inform patients with these MYOC mutations whether they are at a higher risk of developing glaucoma before irreversible vision loss occurs." (PMID 34828408, 2021). "Inherited forms of glaucoma may be attributed to single gene mutations, like myocilin (MYOC) and optineurin (OPTN), however these cases are rare and tend to occur early in life." (PMID 33413217, 2021). "Myocilin (MYOC) is a glycoprotein encoded by a gene associated with glaucoma pathology." (PMID 34356541, 2021). "This event is specific for glaucoma, as myocilin amyloids are the only known form of pathogenic proteins that accumulate within the ER of TM cells, and TM cells are particularly vulnerable to myocilin toxicity." (PMID 33925820, 2021). "GAS7 may interact with other genes implicated in glaucoma pathogenesis such as MYOC, OPTN, WDR36, CAV1, nitric oxide synthase 2 (NOS2), forkhead box C1 (FOXC1), apolipoprotein E (APOE), amyloid precursor protein (APP), and clusterin (CLU)." (PMID 32545285, 2020). "MYOC glaucoma-related mutations may activate inflammatory responses by activating the IL-1/NF-κB pathway." (PMID 32410836, 2020). "Until now, studies have reported more than 70 MYOC mutation sites in glaucoma patients." (PMID 32410836, 2020). "As a case study for how antibodies might not necessarily reveal the whole story of a system, we consider the case of glaucoma-associated myocilin." (PMID 31067323, 2019). "Finally, the MYOC genetic mutation was negatively associated with steroid-induced glaucoma in a recent study." (PMID 31805140, 2019). "This information could aid physicians in early identification of patients carrying a pathological MYOC mutation and at high risk for glaucoma." (PMID 30395621, 2018). "Genetic polymorphismsof MYOCalter the myocilin protein,which leads to disruption of thenormal regulation of intraocular pressure (IOP) that ultimately causes glaucoma.Theaim of the present study was to identify the polymorphism in exon 3 of the MYOC gene of theglaucoma patients in Lahore, Pakistan." (PMID 29630620, 2018). "Myocilin (MYOC) is the gene with mutations most common in glaucoma." (PMID 30395621, 2018). "We speculate that a person carrying the mutant MYOC mutation will likely have a glaucoma phenotype and may also have undiagnosed muscle ailments or vice versa, both of which will have to be monitored and treated." (PMID 30395621, 2018). "To date, the function of wild-type MYOC remains unknown and how mutant MYOC causes high intraocular pressure and glaucoma is ambiguous." (PMID 30395621, 2018). "Despite intense study, it is unknown definitively how mutant MYOC causes glaucoma and the function of wild-type (wt) MYOC has remained elusive." (PMID 30395621, 2018).
glaucoma (continued). "If people with a pathologic MYOC mutation have a skeletal muscle phenotype, this information may aid physicians in early identification of those at high risk for glaucoma." (PMID 30395621, 2018). "People carrying a pathologic MYOC mutation are at extremely high-risk to develop glaucoma, and information that contributes to early identification of these individuals is essential for immediate intervention to help limit the impact of this devastating and blinding disease." (PMID 30395621, 2018). "Increased accumulation of aggregated proteins such as myocilin has been associated with glaucoma." (PMID 29805843, 2017). "Our results therefore indicate that ARS patients could be affected by similar glaucoma pathogenic pathways as JOAG patients with MYOC mutations." (PMID 28575017, 2017). "Its level has also been shown to be elevated in glaucoma and its overexpression increases the collagen expression level while, its induction by glucocorticoids caused the up-regulation of important glaucoma-related proteins including fibronectin, myocilin and MMP1." (PMID 28264047, 2017). "Exocytosis in glaucoma is involved in glutamate excitotoxicity, ATP secretion, and potentially MYOC secretion, indicating novel pathogenic mechanisms through which FOXC1 might promote glaucoma." (PMID 28575017, 2017). "Despite extensive studies on their effects on the HTM, it is not clear whether ROCK inhibitors can correct TGFβ2-induced fibrotic ECM build-up and myocilin over-expression, which have been linked to glaucoma." (PMID 27924833, 2016). "Two variants (p.A10S in TRMU and.G185S in ACADS) also appear in HGMD, and are flagged as “clinically associated” in dbSNP, p.R76K in MYOC was believed to contribute to glaucoma in a di-genic inheritance and p.G5R in LIPA was shown in a functional assay to cause reduced enzymatic activity." (PMID 27175728, 2016). "Besides elevated IOP, glaucoma is also thought to arise from a mutation in a single gene or a group of genes; for instance, it is well identified that MYOC mutations are a major cause of glaucoma." (PMID 25250333, 2014). "Optineurin (OPTN) and myocilin (MYOC) are two genes linked to glaucoma." (PMID 25250333, 2014). "Mice engineered to carry a human MYOC gene with the Tyr43His mutation develop elevated intraocular pressure and glaucoma that may be related to accumulation of misfolded mutant MYOC protein in key structures of the eye." (PMID 24883232, 2014). "Interestingly, MYOC, the first glaucoma gene discovered, encodes a GC-induced protein called myocilin." (PMID 23451275, 2013). "Mutations in the MYOCILIN gene (MYOC) are involved in different types of glaucoma." (PMID 23342144, 2013). "The p.Arg368His mutation has been associated with GLC3A and glaucoma, and could act in digenic early-onset; this mutation may act as a modifier of the MYOC mutant phenotype." (PMID 23922489, 2013). "Cytochrome P450, family 1, subfamily B, polypeptide 1 (CYP1B1) and myocilin, trabecular meshwork inducible glucocorticoid response (MYOC) mutations were identified in early-onset glaucoma in humans, whereas mutations in the CYP1B1 and FOXC1 were detected in mice with early-onset glaucoma." (PMID 23401651, 2013). "Myocilin is a broadly expressed protein that when mutated uniquely causes glaucoma." (PMID 24367514, 2013). "Glaucoma myocilin mutations impair the secretion and proteolytic processing of the protein." (PMID 23342144, 2013). "However, the percentage of mutations (9/207=4.4%) in MYOC associated with glaucoma is relatively low in our population." (PMID 23922489, 2013). "Among the five known glaucoma-causing genes– MYOC (myocilin), CYP1B1 (cytochrome P450, family 1, subfamily B, polypeptide 1), OPTN (optineurin), WDR36 (WDR36), and LTBP2 (latent transforming growth factor beta binding protein 2)–all except WDR36 were identified in three of the studies." (PMID 22312193, 2012). "In this study, we investigated the molecular mechanisms by which MYOC mutants cause glaucoma." (PMID 22615763, 2012).
glaucoma (continued). "We identified two novel probable glaucoma-causing MYOC mutations (Thr209Asn and Leu215Gln)." (PMID 22933836, 2012). "The exact role of myocilin and its functional association with glaucoma are still unclear." (PMID 23082156, 2012). "Currently, there are 85 glaucoma causing mutations listed in the comprehensive myocilin database." (PMID 22550394, 2012). "Two of the most common glaucoma-causing variants of MYOC worldwide are Gln368STOP and Thr377Met." (PMID 23304066, 2012). "Myocilin is a gene linked to the most prevalent form of glaucoma, a major blinding disease." (PMID 23028669, 2012). "Likewise in glaucoma, common pathogenic mutations had been found in unaffected individuals suggesting an incomplete penetrance, such as the MYOC p.Thr377Met, OPTN p.Glu50Lys, and WDR36 p.Asp658Gly." (PMID 22815630, 2012). "We believe these findings do significantly impact our understanding of MYOC-caused glaucoma and could provide the basis for the potential development of a broad-spectrum therapy for the mutant disease." (PMID 22615763, 2012). "Glaucoma patients with myocilin mutation tend to have high IOP." (PMID 23028669, 2012). "In our study, only one carrier of a MYOC mutation claimed to have a parent with glaucoma." (PMID 21552496, 2011). "Clinical characteristics of the myocilin mutation in China glaucoma families." (PMID 21677793, 2011). "A gain-of-toxic-function is thought to underlie the pathophysiology of myocilin glaucoma." (PMID 21283635, 2011). "The molecular mechanisms that lead to glaucoma are not well established but are of significant biomedical interest given that glaucoma is a leading cause of blindness worldwide, and early-onset myocilin glaucoma accounts for ∼4% of glaucoma cases, primarily afflicting children." (PMID 21283635, 2011). "Most carriers of OPTN and MYOC mutations develop glaucoma and asymptomatic carriers are rare." (PMID 21321670, 2011). "Additionally, mutations in myocilin (MYOC), a gene generally associated with early onset (juvenile) primary open angle glaucoma, have occasionally been reported in PCG." (PMID 22737346, 2010). "In addition to said loci and genes associated with PCG, mutations in the gene coding myocilin (MYOC) — a gene generally associated with early-onset primary open angle glaucoma — occasionally have been reported in PCG patients." (PMID 19898634, 2009). "Myocilin has been associated with congenital glaucoma and 2–4% of primary open angle glaucoma (POAG) cases, but the pathogenic mechanisms remain largely unknown." (PMID 19148291, 2009). "Several lines of evidence indicate that MYOC-associated glaucoma may be attributed to a gain-of-function disease model such that intracellular protein accumulation leads to cellular toxicity and cell death." (PMID 19148291, 2009). "MYOC is one of few genes that have been linked to the incidence of glaucoma." (PMID 19148291, 2009). "Myocilin (MYOC) at GLC1A has been established as a direct cause of glaucoma." (PMID 19784393, 2009). "P370L as a heterozygous mutation was identified in MYOC in the affected members but not in the normal individuals, and the mutation cosegregated with the disorder within the pedigree, suggesting that MYOC may be the glaucoma-causing gene in this family." (PMID 19668597, 2009). "Like MYOC-associated glaucoma in humans (in particular juvenile onset), the fluid discharge phenotype observed in the transgenic flies that overexpress intact or mutant MYOC is likely to result from ocular hypertension and causes a rapid and progressive deterioration of visual function." (PMID 19148291, 2009). "The aim of the current study was a similar evaluation of PEG patients for the presence of mitochondrial abnormalities and nuclear gene mutations associated with various types of glaucoma (MYOC, OPTN, WDR36, and CYP1B1) and certain inherited optic neuropathies (OPA1 and OPA3)." (PMID 18246027, 2008). "The Thr377Met MYOC mutation was identified in over half of the glaucoma patients." (PMID 18449353, 2008).
glaucoma (continued). "We reasoned that if glaucoma mutations increased the molecular size of myocilin aggregates, then they could obstruct AH outflow and hence raise IOP." (PMID 19023451, 2008). "MYOC was the first gene in which mutations were found to cause glaucoma." (PMID 18728751, 2008). "We have screened for myocilin (MYOC) gene mutations in a glaucoma family of five generations." (PMID 18776955, 2008). "Thus, the MYOC gene is the only glaucoma gene that has been widely evaluated and is accepted to be a causal gene for glaucoma in many populations." (PMID 18334962, 2008). "The incidence of the Thr377Met MYOC variant in the glaucoma patients was 59% (13/22)." (PMID 18449353, 2008). "The age of the glaucoma patients reflected the previously reported age ranges for MYOC mutations." (PMID 18449353, 2008). "The mechanism by which mutant myocilin causes the glaucoma phenotype remains elusive." (PMID 19023451, 2008). "Further studies are required to determine whether the AH and extracellular matrix from glaucoma patients carrying heterozygous MYOC mutations contains myocilin heteroaggregates." (PMID 19023451, 2008). "Interestingly, it is generally associated with late glaucoma onset (mean age at diagnosis 54.9 years) and low IOPs compared to other MYOC mutations." (PMID 17615537, 2007). "Clinical features of glaucoma patients with pathogenic myocilin mutations." (PMID 17615537, 2007). "Additionally, we also found the novel myocilin mutation Arg346Thr in patient number 19 who was diagnosed with glaucoma at 44 years and showed a narrow-angle." (PMID 17615537, 2007). "We obtained 278 known MYOC variants that exhibit Mendelian inheritance from the MYOC allele-specific glaucoma phenotype database; of the 278 MYOC germline mutations, 105 manifest a glaucoma phenotype, while 173 were identified as neutral polymorphisms or mutations with unknown pathogenicity." (PMID 38397193, 2024). "Additionally, glaucoma-causing MYOC stabilizing mutations may contribute to its pathogenesis via an alternative pathway not involved in ER stress induction." (PMID 38397193, 2024). "However, given FOXE3-associated glaucoma is a consequence of anterior segment dysgenesis, and MYOC contributes to glaucoma through accumulation of mutant MYOC protein aggregates, we suspect differential expression of these genes is unlikely to contribute to PEX glaucoma." (PMID 35348588, 2022). "However, the role of the MYOC mutation in glaucoma remains elusive." (PMID 35652098, 2022). "Furthermore, MYOC is one of the pathogenic genes definitely linked to glaucoma." (PMID 35652098, 2022). "Moreover, obesity may be correlated with the pathogenesis of juvenile OAG, such as mutation of the CYP1B1 gene or the glaucoma-associated olfactomedin domain of myocilin." (PMID 34501469, 2021). "The results of our study provide knowledge for patients with MYOC mutations concerning their risk for developing glaucoma in the future and may minimize irreversible vision loss through increased screening for patients at risk for glaucoma diagnosis." (PMID 34828408, 2021). "In addition to finding genes by which each of the mutants may exert their damage, we were interested in searching for a common altered gene whose mechanism of action could potentially be applied to all MYOC-causing glaucomas." (PMID 22615763, 2012). "Finally, although several mechanisms are bound to be involved in the association of MYOC mutants to glaucoma, it looks that activation of cysteine protease inhibitors could be a common, general one." (PMID 22615763, 2012). "Despite extensive research, it remains unclear how myocilin mutations lead to glaucoma." (PMID 22933836, 2012). "Since mutation of myocilin leads to the early onset of glaucoma, we speculate that mutation of ZO-1, a gene located on the same chromosome region as myocilin (15q), may also lead to the pathology of glaucoma." (PMID 20090922, 2010).